RNU6ATAC27P (RNA, U6atac small nuclear 27, pseudogene)
Gene: Small nuclear RNA gene on chromosome 1 (28,481,362 to 28,481,480, forward strand). Ensembl gene ENSG00000221216.
Homologues: Orthologues: chimpanzee RNU6ATAC27P (98% identical). Paralogues in human: RNU6ATAC (92% identical), RNU6ATAC7P (87% identical), RNU6ATAC41P (86% identical), RNU6ATAC21P (85% identical), RNU6ATAC6P (84% identical), RNU6ATAC8P (84% identical), RNU6ATAC19P (68% identical), RNU6ATAC39P (59% identical), RNU6ATAC22P (55% identical).